TGFB1 (transforming growth factor beta 1)
Diseases named in the same sentence as TGFB1 in open-access papers (continued):
Sharing a sentence is not in itself a finding about the gene and the disease.
colorectal cancer (continued). "GRAIL analysis revealed 19 regions with a significant score, including the strongest connections with TGF-β signalling pathway genes such as TGFB1, SMAD7 and BMP4, thus suggesting a pivotal role of this pathway in colorectal cancer development." (PMID 27145994, 2016). "On the other hand HCT-116 cell line are undifferentiated colorectal carcinoma cells that don’t express COX2 and are positive for transforming growth factor beta 1 (TGF beta 1) and beta 2 (TGF beta 2) expression." (PMID 26896068, 2016). "Besides, TGFβ1-induced FSTL1 binding to Vimentin activates focal adhesion signaling, promoting colorectal cancer cell migration, invasion, and metastasis." (PMID 38605354, 2024). "The results showed that while SERPINE1 expression was significantly different between colorectal cancer and normal tissue, TGFB1 expression was not." (PMID 34215248, 2021). "The identified connections showed that there was a higher-than-expected degree of connectivity, with a significance of PGRAIL<0.05 being observed for TGFB1, SMAD7 and BMP4. rs2238126 in ETV6 presented a weaker than expected connection with other genes reported in previous GWAS of colorectal cancer." (PMID 27145994, 2016). "At the invasive front of colorectal carcinoma the cytoplasmic accumulation of LAM5γ2 in neoplastic cells is the result of synergistic activation of the LAMC2 gene by β-catenin, TGFβ1, and hepatocyte-growth factor (HGF), molecules that all have been variably involved in the pathogenesis of IPF/UIP." (PMID 16813649, 2006). "A lower TGFβ1 level was observed in patients with colorectal cancer compared with controls, which may have been resulted from the elevated CD105/TGFβ1 complex levels in the same patients." (PMID 12778073, 2003). "For this reason, the obtained high expression of the TGFB1 gene in patients with low-advanced colorectal cancer may be a negative prognostic indicator of the disease course." (PMID 35798776, 2022). "While not fully characterized in colorectal cancer, inhibition of TGFβ3 in preclinical models of glioblastoma multiforme is associated with decreased expression of downstream SMAD oncogenes, decreased tumor invasiveness, and dampened TGFβ1/TGFβ2 signaling." (PMID 36382087, 2022). "In conclusion, this study demonstrates that MVD quantified using a Mab to CD105 is an independent prognostic parameter for survival of patients with colorectal cancer, and that plasma levels of CD105, TGFβ1, TGFβ3 and CD105/TGFβ complexes may be useful markers for assessing disease progression." (PMID 12778073, 2003). "Quantification of circulating CD105, its ligands TGFβ1 and TGFβ3 and the ligand–receptor complexes revealed elevated levels of CD105, TGFβ3, CD105/TGFβ3 and CD105/TGFβ1 complexes but not TGFβ1 in patients with colorectal cancer." (PMID 12778073, 2003).
prostate carcinoma (731 papers, 1994 to 2026). A carcinoma that arises from epithelial cells of the prostate gland. "Overexpression or dysregulation of TAF1, driven by genetic and epigenetic changes, was found in NSCLC, where it activates TGFβ1 and is associated with progression of human prostate cancers to the lethal castration-resistant state, is common in various cancers." (PMID 41155227, 2025). "In this study, we investigated the association between genetic polymorphisms in TGFB1 and clinicopathological characteristics or oncological outcomes in patients with prostate cancer during ADT by cancer stage." (PMID 34113577, 2021). "A previous study showed that genetic variation in TGFB1 (509C>T, rs1800469) was associated with Gleason score and tumor stage in prostate cancer." (PMID 34113577, 2021). "In this study, we investigated the association between genetic polymorphisms in TGFB1 and clinicopathological characteristics or oncological outcome in prostate cancer cases treated with androgen-deprivation therapy (ADT) according to metastasis status." (PMID 34113577, 2021). "In one such study, the TGFβ1 rs1800469 C–509T homozygous TT genotype was found to be associated with an increased risk of having an aggressive form of prostate cancer, but the rs1982073 T+29C (T+29C) C variant genotypes were not." (PMID 23840350, 2013). "Indeed, in human prostate cancer, overexpression of TGFβ1 correlates with collagen I levels, suggesting that TGFβ can be directly linked to the desmoplastic process." (PMID 34885243, 2021). "Moreover, rs1982073 (T+29C) and rs1800469 (C-509T) have been linked with increased serum levels of TGFβ1 and with the incidence of invasive breast cancer; rs1800469 (C-509T) has also been linked with advanced-stage prostate cancer and colon cancer." (PMID 23840350, 2013). "The androgen receptor binds to regulatory regions of genes involved in the canonical TGFβ signaling pathway, and in prostate cancer, the androgen receptor interacts with androgen response elements (AREs) in the TGFB1 promoter to regulate its transcription." (PMID 40024947, 2025). "NUSAP1 has also been shown to participate in epithelial-mesenchymal transition by regulating FAM101B, an effector molecule of the TGFβ1 signaling pathway, thus promoting the invasion, migration, and metastasis of prostate cancer." (PMID 38441732, 2024). "TGFβ1 enhances IL-8 promoter activity in prostate cancer cells, while TGFβ1 also regulates IL-8 expression in SUM149 and MDA-MB-231, facilitating cancer stem cell expansion." (PMID 38672477, 2024). "Prostate cancer exosomes triggered TGFβ1-dependent fibroblast differentiation to a distinctive myofibroblast phenotype resembling stromal cells isolated from cancerous prostate tissue; supporting angiogenesis in vitro and accelerating tumor growth in vivo." (PMID 37456240, 2023). "In the process of TGFβ1 induced EMT in the prostate cancer cell line DU145, H3K4me3 enrichment and RbBP5 binding increased in the vicinity of the Snail (SNAI1) transcription start site." (PMID 36319643, 2022). "In autophagy induction, MSCs secrete TGFB1 and preventing TGFB1 secretion inhibits autophagy, leading to increased docetaxel sensitivity of prostate cancer cells." (PMID 35317831, 2022). "We applied comprehensive genotyping for TGFB1 and TGFBR1 polymorphisms in relation to acute and late side effects of radiotherapy in prostate cancer." (PMID 34771749, 2021). "In a single prostate carcinoma cell line, the mitogenic function of TGFβ1 was dependent on ERK signaling." (PMID 33802809, 2021). "In a prostate cancer cell line, where mitogenic conversion of TGFβ1 required oncogenic HRASG12V, p21WAF1 has been identified as a potential executor of this program." (PMID 33802809, 2021). "Overexpression of ANRIL in prostate cancer cells increased cell proliferation and migration by regulating the let-7a/TGFB1/Smad signaling pathway, demonstrating the potential molecular mechanism by which this lncRNA mediates cancer progression." (PMID 34946977, 2021).
prostate carcinoma (continued). "The prostate cancer cells release exosomes that harbor transforming growth factor-beta 1 (TGF-β1), which is involved in the induction of myofibroblast (MFB) transition." (PMID 34805155, 2021). "Several studies have reported an association of genetic polymorphisms in TGFB1, which encodes TGF-β1, with cancer phenotypes in prostate cancer." (PMID 34113577, 2021). "For instance, the co-culture of preadipocytes suppresses AR expression through the up-regulation of miR-301a expression in prostate cancer cells, resulting in the up-regulation of TGFβ1, Smad, and MMP9 expression for metastasis." (PMID 32971847, 2020). "A previous report demonstrated consistently that increased infiltration of Pref-1 and CD29 positive preadipocytes promote prostate cancer metastasis via the mR301a/AR/TGFβ1/Smad/MMP9 pathway." (PMID 32971847, 2020). "It has been reported that treatment with DHT, a product of HSD17B6, inhibited the expression of TGFB1 in prostate cancer." (PMID 32514254, 2020). "Enhanced production of TGFβ1 and decreased TGFβ type II receptor expression constitute poor prognosis factors due to raised metastatic and angiogenic potential in prostate cancer." (PMID 32585812, 2020). "Secondly, TGFB1 actively decreases gastric cancer but increases tumor progression in prostate cancer." (PMID 31205821, 2019). "A subsequent study revealed that αvβ6 was required for TGFβ1-mediated MMP-2 expression in prostate cancer cells." (PMID 31438626, 2019). "In silico analysis to map the function of these secreted factors identified PAPPA, IGFBP2, DKK1, and TGFβ1, which have documented effects on “invasion of tumor cells” or “prostate cancer and tumors”." (PMID 29088840, 2017). "Levels of lymphotoxin β and Transforming growth factor beta 1 (TGF-β1), two cytokines previously reported to be implicated in prostate cancer, were assessed in mouse prostates by ELISA." (PMID 29212195, 2017). "Beneficial therapy outcome was also reflected in the decreased plasma level of TGFβ-1, a molecule often acknowledged as a prognostic marker in prostate cancer." (PMID 28270133, 2017). "Researchers have shown that treating prostate cancer cells with TGFβ1 induced rapid formation of lamellipodia and cytoskeletal rearrangements." (PMID 27863394, 2016). "TAGLN has previously been reported to be upregulated in TGFβ1-induced stromal myofibroblasts, generating a phenotype that resembled reactive stromal cells from patients with prostate cancer." (PMID 26934553, 2016). "In this study, we show CD44, in response to TGFβ1, regulates the mesenchymal phenotype in prostate cancer cells." (PMID 25483103, 2015). "Transforming growth factor beta 1 (TGFβ1) is induced by mifepristone and triggers apoptosis in LNCaP-C4 prostate cancer cells." (PMID 25252652, 2015). "The aim of the current study was to investigate the alterations of phenotypic events in the long-term exposure of prostate cancer (PCa) cells to TGFβ1 and its effect on macrophage-differentiated cells." (PMID 25202359, 2014). "In human prostate cancer (PCa) tissues, TGFβ1 expression is increased compared with normal or benign prostate tissues, and is increased in PCa with lymph node metastasis compared with cancer without lymph node involvement." (PMID 25202359, 2014). "Consistent with our data, TGFB1 was identified as a HO-1 target gene in a microarray comparison of prostate cancer cells with varying HO-1 protein levels)." (PMID 20667089, 2010). "The interaction of ECM proteins with the TβRI in the migratory prostate cancer cells in response to TGFβ1 was demonstrated by several different techniques to reveal that THBS1 mediates cell migration by interacting with integrin subunit alpha V (ITGAV) and TβRI." (PMID 39304722, 2024). "Furthermore, we identified a higher percentage of TGFB1 overexpressed subclonal population (scRNA-seq) in aggressive taxane-resistant DUTXR compared with taxane-sensitive DU145 prostate cancer subtypes." (PMID 37476073, 2023).
prostate carcinoma (continued). "Furthermore, CD44 was upregulated upon TGFB1-induced EMT, and our study reported overexpression of TGFB1 in aggressive prostate cancer (3.41-fold in GE and ∼2-fold protein)." (PMID 37476073, 2023). "Periprostatic mature adipocytes could also release TGFβ1 upregulated connective tissue growth factor (CTGF) expression in prostate cancer cells favoring migration." (PMID 35463353, 2022). "The aim of study was to evaluate the influence of TGFB1 C-509T and Leu10Pro, XRCC1 Arg280His and XRCC3 Thr241Met polymorphisms as well as the level of radiation-induced CD8 T-lymphocyte apoptosis (RILA) on adverse effects of RT for prostate cancer (PCa)." (PMID 36494413, 2022). "In the process of bone metastasis in lung, breast, and prostate cancer, tumor-driven osteoclastogenic factors, such as TGFβ1, PTHLH (parathyroid hormone-like hormone), and MMP-2 (Matrix metalloproteinase-2), facilitate osteolysis and homing of cancer cells to bone." (PMID 33917757, 2021). "TGFB1 is often up-regulated in tumor cells and highly secreted into the prostate environment, partially mediating the immunosuppressive effect on NK cells and promoting the invasion and metastasis of prostate cancer." (PMID 33758613, 2021). "Furthermore, an increased level of TGFβ1 expression was reported in AA prostate cancer patients compared to the CA counterparts." (PMID 33996789, 2021). "Clinicopathological characteristics of patients with non-metastatic prostate cancer according to TGFB1 polymorphisms." (PMID 34113577, 2021). "Using PacMetUT1 cells, suppression of TGFβ signaling via shRNA knockdown of TGFβ1 or usage of inhibitors in a metastatic nude mouse model further revealed how TGFβ impacts osteoblastic metastasis of prostate cancer." (PMID 32585812, 2020). "Moreover, it was found that NUSAP1 promotes the invasion, migration, and metastasis of prostate cancer cells by regulating FAM101B which is regarded as a TGFβ1 signaling effector related to epithelial to mesenchymal transition (EMT)." (PMID 31729978, 2019). "However, a single lncRNA can regulate multiple target genes, for example, H19 targets TGFβ1 in prostate cancer cells, and TGFβ1 is a key regulator in CCA inflammation, suggesting the pivotal role of inflammation regulation by special lncRNAs." (PMID 30305026, 2018). "In addition, prostate cancer exosomes triggered TGFβ1-dependent fibroblast differentiation resemble stromal cells isolated from cancerous prostate tissue, which accelerates tumor growth by supporting angiogenesis." (PMID 26156517, 2015). "Represses prostate cancer metastasis through TGFβ1 via H19/miR-675." (PMID 26110379, 2015). "This could indicate that EPHB4, ITGB8 and TGFB1 are intrinsically regulated in prostate cancer cells, therefore contributing to cancer progression and metastasis through the process of EMT." (PMID 25886373, 2015). "Our data also suggest that ERRα may participate in the initial expansion of cancer cells by regulating the extracellular matrix component postn in stromal cells infiltrating tumors at least in part through the regulation of TGFb1 in prostate cancer cells (pathway 4)." (PMID 27776343, 2016). "BMPs are a diverse class of growth factor proteins that belong to the transforming growth factor-β (TGFB1, TGFB2, TGFBR1, TGFBR2) superfamily, and aberrant expression of various BMPs has been reported in several tumor tissues, including prostate cancer." (PMID 40596459, 2025). "ESS2 tends to be highly expressed in prostate cancer patients, and expression levels of some ESS2 target genes, such as LIF, WNT5A, and TGFB1, were significantly correlated with ESS2 levels in prostate cancer patients." (PMID 40362295, 2025). "In prostate cancer, P2RX4 is involved in enhancing tumor formation, mobility, TGFβ-1 induced invasiveness, and epithelial-to-mesenchymal transition." (PMID 36333684, 2022). "In prostate cancer, EGR1 induces TGFβ1 expression which stimulates tumor tissue growth and angiogenesis." (PMID 35906698, 2022).
prostate carcinoma (continued). "It was also observed 1,25(OH)2D3 or vitamin D analog regulated mRNA expression of several BMP forms i.e., BMP6 in primary prostate cancer cells, BMP2 and BMP6 in MCF10AT1 cells, and TGFβ1 and BMP2A in squamous cell carcinoma lines." (PMID 34208589, 2021). "Simvastatin prevents TGFβ1-induced EMT in lung and prostate cancer cells by arresting phosphorylation of Smad2 and Smad3 proteins." (PMID 34220337, 2021). "Via comprehensive genotyping of TGFB1 and TGFBR1, promising biomarkers for radiotoxicity in prostate cancer were identified." (PMID 34771749, 2021). "We investigated 40 germline polymorphisms in peripheral blood cells, covering the entire common genetic variability in the TGFβ1 ligand (gene TGFB1) and the TGFβ receptor-1 (TGFBR1) in 240 patients treated with primary radiotherapy for prostate cancer." (PMID 34771749, 2021). "Previously, we found that endogenous Gαi2 is essential for cell migration and invasion in prostate cancer cells in response to different stimuli, such as EGF, OXT, TGFβ1 and SDF-1α." (PMID 32575572, 2020). "Previous studies showed that SPDEF is required for CDH1 expression in prostate cancer cells and that SPDEF is a downstream target of TGFB1." (PMID 28076331, 2017). "Exosomes were purified from prostate cancer DU145 cells and were previously shown to contain around 7pg of TGFβ1 per μg of exosomes." (PMID 25596732, 2015). "Regulation of TGFβ1 expression by tissue oxygenation remains unstudied in CRC, although HIF-1α has been shown to increase TGFβ expression in prostate cancer cells." (PMID 24180698, 2013). "TGFB1 has diverse roles in tumor biology, including neuronal development and survival, while SEMA4F has been shown to regulate neurogenesis and axonogenesis in prostate cancer." (PMID 40805163, 2025). "We further confirmed that TGFβ1-induced THBS1 is important for cancer cell invasion, as the knockdown of THBS1 in vitro, or knockdown of TβRI both in vitro and in vivo, inhibited the invasion of prostate cancer cells." (PMID 39304722, 2024). "It has been demonstrated that ERRα expression is correlated with castration-resistant prostate cancer, and it could promote tumor progression by targeting a number of cancer-related genes, including VEGF-A, WNT5A and TGFβ1, and WNT11 and HIF-1α." (PMID 33014785, 2020). "Therefore, it was demonstrated that TGFβ1 regulated MRC2 expression in HCC, which is consistent with the findings in prostate cancer and glioblastoma multiforme." (PMID 25162823, 2014). "An extensive study launched to test formerly reported associations of candidate gene markers (including TGFB1, but not TGFBR1) for impact on early or late side effects of radiotherapy in breast and prostate cancer did not prove a statistically significant risk for any of the markers tested." (PMID 34771749, 2021). "It impeded LPS-dependent EMT in prostate cancer cell lines (PC-3 and LNCaP) through blocking of the Hh signaling pathway and impeded the EMT process in colorectal cancer cells through overexpression of E-cadherin and suppression of vimentin by blocking the TGFβ1/Smads signaling pathway." (PMID 34220337, 2021). "Finally, the correlation between TGFB1 variation and genetic polymorphism in TGFBR or the expression of TGF-β receptor in prostate cancer has not been investigated." (PMID 34113577, 2021). "In contrast to previous investigations in colorectal and prostate cancer cells 19, Vimentin was inhibited after NDRG1 silencing in MDA-MB-231 and MDA-MB-436 cells treated with TGFβ1, which was not seen in SUM159 and BT549." (PMID 36594086, 2023).
prostate carcinoma (continued). "Although TGF-β signaling does not seem to regulate expression of NCK1-AS1, this lncRNA was highly expressed in prostate carcinomas and underexpressed in normal or even benign hyperplastic prostate tissue and seems to activate TGFB1 mRNA and TGF-β signaling via as yet unknown molecular mechanism." (PMID 38571882, 2024).